STAT3 (signal transducer and activator of transcription 3)
Diseases named in the same sentence as STAT3 in open-access papers (continued):
Sharing a sentence is not in itself a finding about the gene and the disease.
tumor (continued). "Conversely, IL-6 has recently been shown in an epithelial tumor cell line to activate NFκB signaling through non-canonical binding of unphosphorylated STAT3 (U-STAT3) to NFκB, releasing inhibition by IκB." (PMID 19436757, 2009). "One of the GBM patients whose MRI was questionable for tumor progression had radiation necrosis confirmed by biopsy; the mean percent of PBMCs displaying p-STAT-3 in this patient was 0.1%, suggesting an absence of tumor." (PMID 19900287, 2009). "Among the 125 tumours, 54 tumours (43.2%) were negative and 71 (56.8%) were positive for p-Stat3 expression." (PMID 19638983, 2009). "It was somewhat surprising that the mean percentage of PBMCs displaying p-STAT-3 did not correlate with the number of tumor cells displaying p-STAT-3." (PMID 19900287, 2009). "Nevertheless, we also detected a diminished STAT3 activation by Western blotting of tumor tissues in the ENMD-1198 treatment group (data not shown), suggesting that the drug also effectively inhibits both targets in vivo." (PMID 18651980, 2008). "The effects of STAT3 activation due to exposure to norepinephrine resulted in an increase in invasion and matrix metalloproteinase (MMP-2 and MMP-9) production, as well as invasion and in vivo tumor growth, which can be ameliorated by STAT3-targeting siRNA.." (PMID 21829284, 2008). "However, constitutively activated STATs, especially STAT1, STAT3 and STAT5, have been found in a variety of human tumours and cancer cell lines, including blood malignancies and solid tumours." (PMID 12865928, 2003). "In HS cells exposed to Dox, CA treatment improved the number of viable tumor cells and decreased the rate of apoptosis, while in HSD cells it enhanced apoptosis as a mechanism of cell death and decreased pro-survival molecules, STAT3 expression in parallel with reduced NRF2 activation." (PMID 42072066, 2026). "The anti-tumor effect of IL-37 results from the suppression of tumor-promoting cytokines, such as IL-1β, which activates IL-6 and TNF, direct effects on tumor cells, and reduction of cell proliferation by interfering with NF-κB, MAPK, and signal transducer and activator of transcription 3 (STAT3)." (PMID 41596472, 2026). "For instance, IL-6 initiates JAK/STAT3 signaling, thereby fostering epithelial–mesenchymal transition (EMT) and the acquisition of cancer stem cell characteristics; this was observed in gastric cancer studies investigating the interplay between CAFs and tumor cells." (PMID 41596524, 2026). "Notably, the early absence of DKK3 alters tumor biology and therapeutic responsiveness to STAT3 inhibition, highlighting its transition from a tumor suppressor to an oncogene." (PMID 41147409, 2026). "Additionally, recent research indicates that BRD7 can downregulate PD‐L1 expression by inhibiting the PI3K/AKT/mTOR/STAT3 signalling pathway, thereby enhancing the cytotoxic function of CD8+ T cells and suppressing immune evasion in NPC, which in turn inhibits tumour growth." (PMID 41510594, 2026). "Finally, a fourth cluster of antigen-presenting CAFs (apCAF), arising predominantly from myeloid cells through MIF-driven JAK/STAT3 signaling, induces an unfavorable CD4+/CD8+ T-cell balance, fosters an immunosuppressive environment, and accelerates tumor progression." (PMID 41439998, 2025). "Mice treated during the initial stages of tumorigenesis displayed significant reduction in tumor burden, reprogramming of the TIME chemokine profile, and augmented dendritic cell (DC) and Th1 responses, supporting the hypothesis that STAT3 contributes to early-stage KM-LUAD development." (PMID 40356899, 2025). "Across multiple tumor types, NSUN2 acts as a positive regulator of tumor progression by stabilizing target RNAs through m5C methylation, enhancing RNA stability, translation efficiency, and splicing, and activating oncogenic signaling pathways (e.g., Ras/PI3K–AKT/ERK, β-catenin, STAT3)." (PMID 41256859, 2025).
tumor (continued). "Our preliminary experimental data demonstrated that highly metastatic tumor cells activate the STAT3 signaling pathway by downregulating SLC9A2, facilitating tumor cell migration and invasion, leading us to hypothesize that STAT3 signaling might also be involved in the angiogenic pathway." (PMID 40474298, 2025). "It drives tumor progression through multiple mechanisms: UCA1 can act as a molecular sponge for tumor-suppressive miRNAs, it modulates signaling pathways like mTOR and STAT3 to enhance glycolysis and proliferation, and it interacts with epigenetic regulators to alter gene expression." (PMID 40918525, 2025). "Given the tumor-promoting role of CD109 and of IL-6 in SCC and the recent findings that CD109 potentiates JAK/STAT3 signaling in lung adenocarcinoma and glioblastoma cells, it was important to establish whether CD109 regulates IL6Rα signaling in SCC and determine the mechanisms involved." (PMID 40317079, 2025). "It has been demonstrated that phosphorylated STAT3 (p-STAT3), which was significantly decreased by MAE, downregulates important pro-metastatic factors like matrix metalloproteinase-9 (MMP-9), which was significantly decreased, effectively inhibiting tumor growth." (PMID 40943427, 2025). "Thus, hypoxia induced tumor derived exosomal ZEB1 was demonstrated to promote immune evasion and escape from innate immune surveillance in cervical squamous carcinoma cells by modifying the activity of the CD47/SIRPα/STAT3 axis." (PMID 39928285, 2025). "In particular, STAT3 has been shown to physically interact with HIF-1α and co-recruit p300/CREB-binding protein (p300/CBP) and RNA-Polymerase II to the vascular endothelial growth factor (VEGFA) promoter in hypoxic tumor cells, thereby reinforcing transcription of angiogenic genes." (PMID 40867898, 2025). "The therapy also reduced levels of p-STAT3 and STAT3 in the TME, decreased the density of α-smooth muscle actin (α-SMA) and CD31 markers, and further increased CD8+ T-cell infiltration, collectively contributing to reduced tumor size, enhanced tumor cell apoptosis, and inhibited tumor growth." (PMID 40281554, 2025). "Targeting STAT3 alone might not comprehensively suppress tumor progression due to compensatory mechanisms and pathway redundancies." (PMID 40860906, 2025). "Through STAT3 activation, CD206+ M2 TAMs sustain a pro-tumor milieu, releasing VEGF, TGF-β, EGF, urokinase-type plasminogen activator (uPA), and multiple matrix metalloproteinases (MMPs), thereby promoting tumor growth, immune suppression, angiogenesis, metastasis, and chemoresistance." (PMID 40948759, 2025). "Soluble factors from tumor cells, including lysophosphatidic acid, CXCL16, Wnt7a, osteopontin, HOXA9, and EVs, are involved in promoting MSC trans-differentiation into CAF-like cells via various signaling pathways such as TGF-β/Smad, miRNAs, STAT3, MAPK, and integrins." (PMID 40676710, 2025). "Our findings revealed a high expression of STAT3 in GBM, and the aberrant activation of STAT3 may be a crucial factor contributing to excessive proliferation of GBM, chemotherapy resistance, as well as the immunosuppressive tumor microenvironment." (PMID 41145734, 2025). "Furthermore, genetic ablation of downstream PERK effectors (CHOP or ATF4) in tumor stroma substantially attenuates MDSC-mediated immunosuppression through downregulation of critical molecular mediators including C/EBPβ, phosphorylated STAT3, and IL-6231." (PMID 41209558, 2025). "At the same time, Rg3 inhibited STAT3 activation, reduced tumor cell secretion of CCL2, reduced the recruitment of MDSCs and TAMs in the lungs, destroyed the metastatic microenvironment, inhibited tumor cell growth and metastasis, increased tumor cell apoptosis, and reduced tumor size." (PMID 40292112, 2025).
tumor (continued). "Aberrant hyperactivation of the JAK2/STAT3 axis is frequently observed in TNBC and has been shown to transcriptionally upregulate anti-apoptotic genes such as Bcl-2 and Survivin, facilitate epithelial–mesenchymal transition (EMT), and promote tumor cell migration, invasion, and immune evasion." (PMID 40936705, 2025). "These include the enhanced phosphorylation of STAT3 (1.2–1.4-fold), which promotes effector T cell differentiation, enhanced phosphorylation of HSP27 (2–2.6-fold), which has an anti-apoptosis function, and reduced phosphorylation of Chk-2 (1.4–2-fold), a tumor suppressor." (PMID 40796680, 2025). "Therefore, although our data suggest that the anti-tumor activity of Atovaquone in TNBC is mediated by suppression of the STAT3 pathway, we cannot rule out the contribution of off-target mechanisms." (PMID 40696387, 2025). "To explore whether STAT3 expression has a role as a prognostic factor, we first compared the overall and disease-free survival (OS and DFS) curves of patients with STAT3+ and STAT− tumor compartments, as well as with a STAT3+ and STAT− immune cell microenvironment." (PMID 40426911, 2025). "Furthermore, Nef significantly decreases the protein expression of COX‐2, iNOS, phosphorylated p65, and phosphorylated STAT3 in both tumor and nontumor tissues." (PMID 40548181, 2025). "Network pharmacology prioritized STAT3, HSP90AA1, CASP3, CASP8, and SRC as core therapeutic targets, with molecular docking confirming stable interactions between these two metabolites and targets, highlighting their potential in managing infections, neoplasms, and metabolic disorders." (PMID 41295287, 2025). "Notably, targeting local STAT3 is challenging because, although STAT3 diminishes CD8+ T cell cytotoxicity and enhances Treg tolerance, it is indispensable for the expansion of memory T cells and long-term tumor immunity." (PMID 40607254, 2025). "In addition, it was demonstrated that changes in CD44 glycosylation regulate its binding to hyaluronic acid, fibronectin, collagen, and podoplanin, and modulates c-Src/STAT3/TWIST1, PI3K/AKT/mTOR, ERK/NF-kB/NANOG and other signaling pathways, modulating TME traits and tumor cells behavior." (PMID 39860065, 2025). "In the AOM/DSS-induced murine CAC model, Th17-related cytokines, including IL-17A, IL-21, IL-22, TNF-α, and IL-6, are produced by tumor-infiltrating lymphocytes (TIL), which could activate the STAT3/NF-κB pathway, thereby promoting CAC cell proliferation and accelerating tumor progression." (PMID 40109347, 2025). "In conclusion, HMP1G NPs downregulated tumor‐derived IDO1 the AhR/STAT3/IL axis, improving KYN/TRP metabolism dysregulation, effectively overcoming metabolic immune suppression within the TME, reversing immunological tolerance in cold tumors, and sensitizing tumor cells to ICB therapy." (PMID 39661740, 2025). "Moreover, GBM cells often exhibit adaptive resistance through the upregulation of alternative oncogenic pathways, including STAT3, PI3K/AKT/mTOR, and MAPK signaling, which can functionally compensate for NF-κB inhibition and maintain tumor survival and proliferation." (PMID 40869207, 2025). "Thus, we hypothesise that IL‐11 mainly exerts its intrinsic pro‐tumourigenic role via STAT3 activation, whereas the PI3K–AKT–mTORC1 or MAPK pathways may be triggered by IL‐11 from other cells in the tumour stroma, thus favouring tumour progression." (PMID 40673604, 2025). "STAT3 activation in pancreatic cancer cells, including those with stem-like traits, directly binds to the VEGF promoter, upregulates VEGF expression, and enhances endothelial cell proliferation and migration, leading to increased angiogenesis and tumor growth in vivo." (PMID 40881675, 2025). "In addition, IL-6-induced STAT-3 activation occurs in tumour-infiltrating immune cells, where it exerts a negative regulatory effect on neutrophils, natural killer (NK) cells, and effector T cells, contributing to an immunosuppressive tumour microenvironment." (PMID 39858001, 2025).
tumor (continued). "In conclusion, our study reveals the critical involvement of SLC9A2 in tumor metastasis and angiogenesis, uncovering a previously unrecognized mechanism by which SLC9A2 facilitates the dephosphorylation of STAT3, thereby suppressing the oncogenic effects of STAT3 signaling in CRC." (PMID 40474298, 2025). "Given the extensive involvement of metabolic and signal transduction pathways in tumor cells, we aimed to identify the key components of T24 cells responsible for CAF activation and to determine whether the CXCL14/CCR7/STAT3/ERCC4 signaling axis is involved in this process." (PMID 40898244, 2025). "While STAT3 itself may not inherently possess oncogenic or tumor-suppressive functions, its activation through phosphorylation leads to dimerization and nuclear translocation." (PMID 40906092, 2025). "This study did not focus on the effect of STAT3 on the proliferation of tumor, but on whether myocardial damage in hypoxia was improved by the activation of STAT3." (PMID 40514732, 2025). "This enhanced inflammatory status or pro-inflammatory profile of the tumor microenvironment has been shown to contribute to increased lipolysis and cancer cachexia in variable types of cancers through PRDM16 gene overexpression via activation of the STAT3 pathway." (PMID 40227577, 2025). "Furthermore, we present existing and new treatment methods that are centered on CAFs, such as suppression of the paracrine pathway (e.g., IL-6/STAT3, TGF-β), depletion of CAFs lineages by targeting fibroblast activation protein (FAP), and conversion toward tumor-restraining CAFs." (PMID 40959080, 2025). "Therefore, we investigated whether the effects of MCPIP1 on tumor EMT and tumor stemness were mediated by targeting the IL6/JAK2/STAT3 signaling pathway." (PMID 40874680, 2025). "STAT3 activation and subsequent tumor development do not occur without the Glycoprotein 130 (gp130) receptor, which is a signaling element of the IL-6R‒gp130 complex, and the IL-6 family member IL-11 is a promotion element of GC by activating STAT3 to overexpress proliferative genes in mice." (PMID 40264171, 2025). "Moreover, STAT3 activation perpetuates disease progression through the STAT3/PKM2/SNAP23 signaling axis, leading to PKM2 phosphorylation, metabolic reprogramming via enhanced glycolysis, and increased exosome secretion by tumor cells." (PMID 41169372, 2025). "This may reflect a distinct biological role of STAT3 in immune regulation rather than tumor proliferation or invasion, providing a possible explanation for the observed discrepancy with the existing literature." (PMID 40426911, 2025). "Given the strong link between HFD consumption and tumor progression, interventions targeting lipid metabolism, macrophage polarization, and pro-survival signaling pathways such as PI3K/AKT and STAT3 may offer promising therapeutic avenues to enhance cancer treatment outcomes in obese individuals." (PMID 40282189, 2025). "lncRNA enhancing IL-6/STAT3 signaling activation (LEISA) recruits transcription factor STAT3 to the IL-6 promoter, establishing a feedforward loop that augments IL-6 secretion and STAT3 phosphorylation to promote tumor proliferation and chemotherapy resistance." (PMID 41409273, 2025). "Activated STAT3 can induce the expression of EMT-related transcription factors, including Snail, ZEB1, and Twist, downregulate E-cadherin expression, and upregulate N-cadherin expression, thereby promoting the EMT process in tumor cells and enhancing their invasive and metastatic capabilities." (PMID 40909292, 2025). "While we did not observe a difference in OS and DFS between patients with or without STAT3 expression in the tumor compartment, we did observe a significant difference in DFS between patients with STAT3+ and STAT3− expression in the immune cell microenvironment." (PMID 40426911, 2025).
tumor (continued). "In addition, tumor cells displayed serine phosphorylation at position 727 in both STAT1 and STAT3, as determined by immunostaining with phospho-serine-specific antibodies directed against STAT1 and STAT3, respectively." (PMID 40287766, 2025). "In addition, the supernatant from STAT3 silenced NSCLC cells promotes the migration of monocyte, which may represent another feasible mechanism to reduce the recruitment of immune cells to tumor sites." (PMID 38693304, 2024). "Furthermore, the absence of HLJ1 contributes to DEN-induced carcinogenesis and proliferation, likely due to increased phosphorylation of STAT3 in adjacent normal tissues rather than in tumor tissues." (PMID 39738726, 2024). "Notably, in tumor-targeted therapy, both curcumin and a novel dimanganese complex (FMSP) have been observed to downregulate CXCR4, thereby promoting the generation of ROS and inhibiting the activation of the STAT3 pathway." (PMID 38920657, 2024). "Interestingly, p‐FAK/p‐MEK/p‐ERK/p‐STAT3 also significantly increased after the addition of exogenous recombinant CCN1, implicating an autocrine/paracrine regulatory mechanism of this secreted protein within the tumor microenvironment." (PMID 39659236, 2024). "However, metastatic tumours from mice lacking STAT3 expression in HStCs (STAT3cKO, Cre+) showed a marked reduction of YM1+ macrophages, while overall macrophage numbers (F4/80+ cells) remained unchanged." (PMID 38678021, 2024). "STAT3 may have a dual role in GBM, either promoting or suppressing GBM tumor progression." (PMID 38474265, 2024). "In addition, CD34, EDIL3, and TPM3 were positively correlated with signaling pathways related to tumor immune response, invasion, and metastasis, particularly the IL6/JAK/STAT3, inflammatory response, TNF-α signaling via NF-kB, and epithelial-mesenchymal transition." (PMID 38840234, 2024). "Moreover, STAT3 and CTLA4 exhibited upregulated profiles in Tregs of UTUC, which could hinder anti-tumor immunity, and suppress the production of immunosuppressive cytokines and metabolites, respectively." (PMID 38903524, 2024). "CMTM family proteins exert their biological functions by regulating signaling pathways related to cell growth and migration, including the EGFR, WNT, and JAK2/STAT3 signaling pathways, suggesting that CMTM proteins may serve as potential targets for modifying tumor development." (PMID 38223763, 2024). "Additionally, treatment of MCF-7 cells with these podophyllotoxin derivatives resulted in suppression of protein expression such as VEGF-A, STAT-3, ERK1/2, ERK-p that regulates the tumour microenvironment suggesting the potential for influencing tumour angiogenesis and invasion." (PMID 39091955, 2024). "Interestingly, STAT3 phosphorylation and gp130 expression were generally high in mouse tumor tissues in vivo, regardless of tumor cell types." (PMID 38274367, 2024). "We noticed that STAT3-induced FGF7 expression in CAFs still occurs even in the absence of tumor cells because STAT3 inhibition by STAT3-IN-11 is sufficient to decrease FGF7 expression, suggesting a regulation of FGF7 expression by the basal activity of STAT3 in CAFs." (PMID 39594574, 2024). "However, in the tumour microenvironment, due to the continuous action of chemical signals from cytokines, JAK activates STAT3 phosphorylation after activation, and p‐STAT3 continues to form a dimer into the nucleus to regulate the transcription of many autophagy‐related genes." (PMID 38506082, 2024). "In contrast, PD-PDX kinases with potential to be restored by the addition of MSCs include ACVR1C (ALK7), MAP3K14 and ROR1, which may be inhibitors of tumour growth, and JAK1, involved in the STAT3 signalling pathway characteristic of the inflammatory molecular subclass of CCA." (PMID 39492622, 2024).